SIRPA (signal regulatory protein alpha)
Diseases named in the same sentence as SIRPA in open-access papers (continued):
Sharing a sentence is not in itself a finding about the gene and the disease.
tumor (continued). "The N-terminal V domain of human SIRPα bind human CD47 on tumor cells and prevent it from delivering inhibitory signals to macrophages." (PMID 33329583, 2020). "This resulted in synergistic effects on tumor rejection also due to the enhanced cross talk between DCs and T cells promoted by the positive effect of SIRPα triggering on DCs." (PMID 32025850, 2020). "The SIRPα-exosomes significantly increased the phagocytic capacity of macrophage, attenuated tumor growth." (PMID 32489584, 2020). "Mice tumor xenograft treated with SIRPα-EEVs showed a reduction in tumor volume compared to untreated mice." (PMID 33126572, 2020). "When CD47 in tumor cells binds to SIRPα in myeloid cells, it leads to suppression of tumor cell phagocytosis and other innate immune functions." (PMID 32448366, 2020). "CD47 is an immune checkpoint protein that downregulates both the innate and adaptive anti-tumor immune response via its counter receptor SIRPα." (PMID 32240171, 2020). "In immunocompetent syngeneic mice, RCC or melanoma cell tumor formation was markedly suppressed by anti-SIRPα antibody through blockade of CD47 interaction." (PMID 32117298, 2020). "Macrophages can be induced to phagocytize tumor cells by CD47/SIRPα-blocking agents, resulting in antigen presentation and promotion of adaptive immune responses against tumors." (PMID 32456204, 2020). "Anti-CD47 antibodies enhance the phagocytosis of tumor cells by macrophages by directly blocking the binding of tumor cell-expressing CD47 to macrophage-expressing SIRPα." (PMID 32082311, 2020). "Exosomes engineered with the variant of signal regulatory protein α (SIRPα) antagonise the interaction between CD47 and tumour cells and between SIRPα and macrophages, and increase tumour phagocytosis." (PMID 32276342, 2020). "Accumulating evidence suggests that the blockade of CD47 and its ligands signal regulatory protein α (SIRPα) are promising in tumor immunotherapy." (PMID 32536914, 2020). "Along this line, a similar proportion of M1 and M2 and a more frequent expression of PD-1 and SIRPα in M2 tumor-promoting macrophages was observed." (PMID 32691208, 2020). "Antibodies blocking the interaction between CD47 on tumor cells and SIRPα on macrophages enhance macrophage phagocytosis, show efficacy in preclinical tumor models, and are being evaluated in the clinic." (PMID 33133093, 2020). "Anti-SIRPα antibodies appear to target neutrophils and macrophages that are contributing to tumor growth in vitro and in vivo." (PMID 35582455, 2020). "Here, we show that elimination of CD47, a ligand for the myeloid cell inhibitory receptor SIRPα, from tumor cells by genetic deletion or antibody blocking, significantly improves the effectiveness of the immune response to tumour cells." (PMID 31996683, 2020). "CD47 expressed by tumor cells binds to signal regulatory protein α (SIRPα) on TAMs suppressing tumor cell phagocytosis." (PMID 32326073, 2020). "Using flow cytometry analysis, we confirmed that the protein levels of Sirpα in TAMs dynamically increased with tumor progression in the MC-38- and CT-26-based subcutaneous tumor models." (PMID 32296015, 2020). "Another study showed that the signal-regulatory protein alpha (SIRPα) modified exosomes for blocking the “don’t eat me” signal via targeting CD47 on tumor cells." (PMID 33374978, 2020). "The mRNA levels of Sirpα in TAMs from different tumor models increased dynamically with tumor growth." (PMID 32296015, 2020). "Binding of CD47 of tumour binding to SIRPα inhibits the phagocytosis of macrophages to evade innate immunological eradication as well as subsequent adaptive immunity." (PMID 33014356, 2020). "RQ treatment decreased the expression levels of CD47 and SIRPα on tumor cells and macrophage cells in co-culture experiments." (PMID 32020472, 2020). "Given the suggested importance of surface expression of corresponding ligands on tumor immune infiltrate, we also examined the same pediatric cancers for SIRPα." (PMID 35582455, 2020).
tumor (continued). "They obtained similar results by grafting the SIRPα N-terminal Ig domain onto rituximab, who played the role of a tumor-specific scaffold." (PMID 32677994, 2020). "Functionally, we showed that the transgenic expression of Elk-1 in macrophages obviously enhanced Sirpα expression, potentiated tumor growth and shortened survival." (PMID 32296015, 2020). "Given that Sirpα is an inhibitory checkpoint molecule in phagocytosis, we next evaluated the phagocytic activity of TAMs in the context of tumor development." (PMID 32296015, 2020). "ADU-1805 blocks CD47 binding to SIRPα and enhances the antibody-mediated tumor cell uptake by phagocytes." (PMID 32025850, 2020). "Again, CD47KO tumor cell vaccination resulted in a significantly increased frequency of CD11c+SIRPα+ (F4/80−CD64−) DCs and their expression of MHC class II I-Ab compared to vaccination with WT tumor cells." (PMID 31996683, 2020). "RQ increased the phagocytic ability of macrophages and decreased the in vitro expression levels of CD47 and SIRPα on tumor cells and macrophages, respectively." (PMID 32020472, 2020). "Anti-SIRPα antagonists have also been combined with tumor-opsonizing antibodies such as rituximab showed anti-tumor efficacy in vitro and in xenograft lymphoma and colon cancer models." (PMID 32677994, 2020). "In particular, given that synergistic action of Sirpα/CD47 blockade and ICBs has been reported in other tumor types, neutralization of Sirpα represents an attractive approach to increase the responsiveness of CRC patients to ICB." (PMID 32962159, 2020). "A further well-known immune escape strategy applied by tumors is the overexpression of CD47, also carried by tumor-derived EV, which interacts with the signal regulatory protein α (SIRPα) on phagocytic cells, limiting their activity." (PMID 33117718, 2020). "Mechanistic studies revealed that rapid expansion of SIRPα+CD11c+ DCs following CD47KO tumor cell vaccination is essential for induction of antitumor responses in these mice." (PMID 31996683, 2020). "SIRPA is expressed on the surface of antigen-presenting cells such as macrophages and plays a critical role in phagocytic engulfment of tumor and other cells." (PMID 30726215, 2019). "Secondarily, decreased phagocytosis impedes anti-tumor adaptive immunity by inhibiting antigen presentation and anti-tumor T cell priming by SIRPα-expressing dendritic cells, microglial cells, and tumor-associated macrophages." (PMID 31276567, 2019). "CD47 is a molecule with an immunoglobulin-like domain that is expressed on tumor cell surface and inhibits macrophage phagocytosis via binding the signal regulatory protein α (SIRPα) on phagocytes." (PMID 30653520, 2019). "Upon binding to CD47 on tumor cells, the cytoplasmic tail of SIRPA becomes tyrosine-phosphorylated, and SHP-1 and SHP-2 phosphatases are recruited and activated, initiating dephosphorylation of downstream substrates." (PMID 30726215, 2019). "It binds to the signal regulatory protein alpha (SIRPα) to prevent cancer cells from undergoing phagocytosis in the tumor environment." (PMID 31709180, 2019). "Accumulating preclinical data indicate that targeting the SIRPα/CD47 axis alone or in combination with existing targeted therapies or immune checkpoint inhibitors enhances tumor rejection." (PMID 31801627, 2019). "Targeting SIRPα enhanced tumor cell uptake by macrophages and neutrophils at a similar rate as anti-CD47 mAbs." (PMID 31801627, 2019). "The expression level of two functional proteins on macrophages were detected including SIRPα, the ligand protein of CD47, and CD68, one of the markers of tumor-associated macrophages." (PMID 31139022, 2019). "The function modifying CD47 antibody B6H12 has been used extensively as an antagonist of CD47 signaling through SIRPα in preclinical studies and demonstrated tumor suppressing activities in many xenograft models." (PMID 31632920, 2019).
tumor (continued). "In brief, these results showed that blocking CD47 by SIRPα-Fc potentiated anti-tumor response of NSCLC to VEGF blockade." (PMID 31829270, 2019). "CD47 is expressed by tumor cells and interacts with the signal regulatory protein-α (SIRPα, also known as SHPS1) expressed on the surface of phagocytic cells, such as macrophages and dendritic cells." (PMID 31878087, 2019). "Interactions between CD47 and SIRPα prevent tumor cells from undergoing phagocytosis, allowing cancer cells to escape immune surveillance." (PMID 31805946, 2019). "A well-characterized mechanism of immune evasion by tumor cells is the up-regulation of the antiphagocytic (“don’t eat me”) surface protein CD47 which binds to its cognate receptor SIRPα on phagocytic cells inhibiting its phagocytic activity." (PMID 30602457, 2019). "This protein binds to the signal regulatory protein alpha (SIRPα) expressed on macrophages and prevents the elimination of tumor cells." (PMID 30814491, 2019). "In presence of rituximab, hSIRPα.40A augmented tumor-cell uptake (calculated using the uptake index) of Raji cells by macrophages obtained from both SIRPA homozygous (SIRPαV1/SIRPαV1 and SIRPαV2/SIRPαV2) and heterozygous (SIRPαV1/SIRPαV2) individuals." (PMID 31801627, 2019). "CD47 is an immune checkpoint molecule that downregulates key aspects of both the innate and adaptive anti-tumor immune response via its counter receptor SIRPα, and it is expressed at high levels in a wide variety of tumor types." (PMID 31276567, 2019). "Masking of CD47 on tumor cells using monoclonal antibody or soluble SIRPα-Fc construct can trigger ADCP of tumor cells by TAMs." (PMID 31805946, 2019). "At 20 weeks from treatment initiation, tumor number and volume per colon were significantly reduced in mice treated with anti‐SIRPα mAb when compared with those in mice treated with isotype‐matched control Ab (P = 0.013, P = 0.001)." (PMID 30460349, 2018). "The average number of F4/80‐positive cells (predominantly macrophages) infiltrating each tumor was also significantly higher in anti‐SIRPα mAb‐treated mice (P = 0.010)." (PMID 30460349, 2018). "Our findings extend the molecular signaling mechanisms downstream to Notch in macrophage polarization and highlight SIRPα as a novel target of Notch-mediated macrophage polarization for tumor therapy." (PMID 30105024, 2018). "In four independent subcutaneous mouse tumor models, we demonstrate that SIRPα blockade combines in a synergistic manner with PD-1 blockade to reduce tumor burden." (PMID 30400822, 2018). "In contrast, anti‐SIRPα mAb exhibited enhanced macrophage phagocytic activity and marked anti‐tumor effects against gastroenterological malignancies." (PMID 30460349, 2018). "Anti‐SIRPα mAb treatment inhibited tumor progression in CPC‐APC mice and significantly improved overall survival." (PMID 30460349, 2018). "Here we demonstrate that, in addition to increasing macrophage uptake of tumor cells in suspension, SIRPα blockade also functions to modify the myeloid compartment in the TME of solid tumors." (PMID 30400822, 2018). "CD47 expressed by tumor cells interact with SIRPα transmitting a “don't eat me” signal to macrophages to avoid being eliminated." (PMID 30525058, 2018). "When expressed by tumor cells, CD47 can bind SIRPα on myeloid cells, leading to suppression of tumor cell phagocytosis and other innate immune functions." (PMID 30133535, 2018). "In this assay, binding of wild-type SIRPα to the Jurkat tumor cell line was measured with fluorescently labeled wild-type SIRPα fused to human IgG1 Fc." (PMID 30133535, 2018). "Agents that block SIRPα directly, such as anti-SIRPα antibodies, also act as adjuvants for tumor-binding antibodies." (PMID 30105024, 2018). "Taken together, our results provided new insights into the molecular mechanisms of notch-mediated macrophage polarization and further validated SIRPα as a target for tumor therapy through modulating macrophage polarization and phagocytosis." (PMID 30105024, 2018).
tumor (continued). "In conclusion, we have demonstrated that anti‐SIRPα mAb exhibits enhanced macrophage phagocytic activity and marked anti‐tumor effects in immunocompetent syngeneic mouse models." (PMID 30460349, 2018). "Consistent with previous reports, overexpression of SIRPα in BMDMs using lentivirus attenuated tumor cells engulfment, and knockdown of SIRPα with siRNA enhanced BMDM phagocytosis." (PMID 30105024, 2018). "Blocking the interaction between CD47 on tumor cells and SIRPα on macrophages has been shown to induce antitumor responses." (PMID 27283989, 2017). "One well-studied immune evasion mechanism involves the interaction of tumour surface-localizedCD47withmacrophage or dendritic surface-localized SIRPα (SIRPA), conveying a “don't-eat-me” signal." (PMID 28886030, 2017). "CD47, expressed on a variety of tumor cells, confers immune resistance by delivering an inhibitory “don't eat me” signal to phagocytic cells via its myeloid-specific receptor SIRPα." (PMID 28061465, 2017). "While CD47 is implicated in the regulation of cancer cell invasion and metastasis, its most well-studied and important function related to tumor development is prevention of phagocytosis via ligating with SIRPα on the surrounding phagocytes." (PMID 28077173, 2017). "Our results hence indicate that the rewiring of CD47 signaling in macrophages by SIRPα Shp2-iSNAP can promote the antibody-mediated tumor cell phagocytosis." (PMID 28883531, 2017). "Taken together, these data suggest that SIRPα expression possibly suppress Wnt/β-catenin signaling and promote Foxo3a expression in tumor cells." (PMID 27010069, 2016). "CD47 expression on tumor cell membranes and subsequent binding to signal-regulatory protein alpha (SIRPα) on macrophages lead to a signal cascade within the macrophages that inhibits macrophage-mediated tumor cell phagocytosis." (PMID 27092773, 2016). "CD47 functions as an inhibitor of phagocytosis, since its interaction with its receptor SIRPα in macrophages leads tumor cells to be recognized as self-molecules." (PMID 27671753, 2016). "Two antibodies that block the interaction of CD47 on tumor cells with SIRPα on macrophages have entered Phase 1 human clinical trials (NCT02216409, NCT02367196, NCT02488811)." (PMID 26813769, 2016). "Neutrophils are recruited to tumor sites through transendothelial migration involving the CD47:SIRPα recognition (signal regulatory protein alpha) creating an inflammatory environment." (PMID 26941482, 2016). "Taken together, our results show that SIRPα expression inhibits the proliferation and promotes the apoptosis of tumor cells." (PMID 27010069, 2016). "In the present work, we designed Polypurine reverse Hoogsteen hairpins, PPRHs, to silence the expression of CD47 in tumor cells and SIRPα in macrophages with the aim to eliminate tumor cells by macrophages in co-culture experiments." (PMID 27671753, 2016). "We showed that PMA-differentiated THP-1 cells eliminated tumor cells after decreasing CD47/SIRPα interaction whereas tumor cells remained unaffected in the absence of PPRHs." (PMID 27671753, 2016). "Signal regulatory protein α (SIRPα) is a cell-surface protein expressed on macrophages that are regarded as an important component of the tumor microenvironment." (PMID 27793032, 2016). "The anti-human CD47 antibody B6H12 inhibits tumor growth in several xenograft models, presumably by preventing SIRPα engagement." (PMID 26840086, 2016). "When transfecting THP-1 cells with HpSIRPαI7-T, the decreased level of SIRPα allowed macrophages to kill 58 % of tumor cells." (PMID 27671753, 2016). "In this work, we explored the usage of specific PPRHs to decrease the expression of CD47 and SIRPα to stimulate the elimination of tumor cells by macrophages, which constitutes a new approach in tumor immunotherapy." (PMID 27671753, 2016).
tumor (continued). "In the present study, we investigated the general pro-apoptotic effect of SIRPα on tumor cells, and as an extension, we studied the role of SIRPα in the ATO-induced apoptosis of APL cells." (PMID 27010069, 2016). "In summary, our results demonstrate that SIRPα inhibits tumor cell survival and significantly contributes to ATO-induced APL cell apoptosis." (PMID 27010069, 2016). "The CD47:SIRPα interaction is involved in the pathogenesis of lung cancer and other cancer types when tumors release cytokines promoting tumor growth and stimulating the conversion of macrophages from M1 to M2 phenotype." (PMID 26941482, 2016). "Our data suggested that CD47 and SIRPα significantly increased in tumor but this was attenuated by PD-1 blockade." (PMID 26573233, 2015). "In conclusion, we provide evidence that proper engagement of CD47 with its receptor SIRPα is crucial for successful establishment of tumor metastases." (PMID 26674012, 2015). "Binding to signal regulatory protein α (SIRPα) can transduce inhibitory signals to decrease the phagocytic activity of macrophages and boost the immunological evasion of tumor cells, as well as tumor development." (PMID 25658794, 2015). "CD47 is expressed on the surface of all human solid tumor cells, and binding to SIRPα blockade of CD47 signaling using targeted monoclonal antibodies enabled macrophage phagocytosis of tumor cells that were otherwise protected in vitro." (PMID 25658794, 2015). "Recent studies have also demonstrated that the CD47-signal regulatory protein α (SIRPα) signaling system plays important roles in tumor immune surveillance through regulation of the phagocytic activity of macrophages." (PMID 26506238, 2015). "Considerable efforts have focused on developing CD47-targeting mAbs to block the CD47/SIRPα antiphagocytic pathway established between tumor cells and immune cells." (PMID 26578962, 2015). "We determined the effect of chimeric SIRPα expression on tumor cell growth and programmed cell death by its triggering with an agonistic antibody in these cells." (PMID 23320069, 2013). "In the TME, such PTMs may determine whether SIRPα sustains an immunosuppressive state favoring tumor progression or shifts toward a pro-inflammatory phenotype that supports antitumor immunity." (PMID 41486149, 2026). "Furthermore, SIRPα on macrophage establishes a direct contact with the CD47/αvβ3‐ECD complex on tumor cells, with an angle of ≈80°–90°." (PMID 41168993, 2026). "Among these, oncolytic adenoviruses (OAds) engineered to locally express SIRPα-Fc have shown efficacy in preclinical tumor models by reprogramming TAMs and DCs toward a pro-inflammatory, antigen-presenting phenotype, leading to enhanced CD8+ T cell responses and synergy with PD-1 blockade." (PMID 41486149, 2026). "However, our SIRPα antibody demonstrated broad expression across tumor cells, lymphocytes, and macrophages." (PMID 41415295, 2025). "In SIRPα−/− mice, tumor responsiveness to RT is contingent upon the presence of SIRPα− macrophages." (PMID 41296731, 2025). "For example, in preclinical studies, pH‐responsive exosome‐nanocouples have been developed by modifying the surface of M1 macrophage‐secreted exosomes with anti‐CD47 and anti‐SIRPα antibodies through acid‐cleavable of dibenzoylethylene bonds, targeting tumor cells." (PMID 39968497, 2025). "CD47 on tumor binds SIRPα on macrophages, inhibiting phagocytosis." (PMID 41346390, 2025). "Radiotherapy mainly upregulates CD47 and SIRPα in the most diverse tumor microenvironments." (PMID 40835598, 2025). "Moreover, these cells are involved in the superior tumor control by combination of RT and anti-SIRPα treatment." (PMID 40208335, 2025). "Notably, myeloid cells with high expression of PD-1, PD-L1, VISTA, and SIRPα were significantly closer to tumor cells compared to those with low expression of these checkpoints." (PMID 40897819, 2025).